CD36 (CD36 molecule (CD36 blood group))
Diseases named in the same sentence as CD36 in open-access papers (continued):
Sharing a sentence is not in itself a finding about the gene and the disease.
Hyperglycemia (continued). "In conclusion, our findings point out an important role of CD36 in mediating the deleterious effect of hyperglycemia and atherogenic lipid molecules on the inflammatory and calcification processes of VSMC involved in the accelerated atherogenesis accompanying these metabolic conditions." (PMID 33028031, 2020). "Moreover, CD36 expression has been previously reported to be altered by hyperglycemia in atherosclerotic patients." (PMID 33028031, 2020). "In the present study, we show that hyperglycemia increased the expression and activity of the oxLDL scavenger receptor-CD36, induced inflammatory and ER stress markers expression, and we demonstrate the contribution of CD36 to in vitro calcification in human VSMC." (PMID 33028031, 2020). "Hence, hypoxia and hyperglycemia decreases the abilities of activated macrophages for phagocytosis because the expression of CD-36 and Class B scavenger are downregulated." (PMID 31415598, 2019). "The results of this study have shown that hyperglycemia is a powerful inhibitor of glycated CD36." (PMID 28729885, 2017). "To determine whether red clover extract attenuates hyperglycemia in diabetic mice by activating PPARγ, we analyzed the mRNA expression of PPARγ, glucokinase and CD36." (PMID 23170129, 2012). "Together with our in vivo observations, these results suggest that hyperglycemia may induce upregulation of CD36 mRNA and protein selectively in proximal tubules in kidneys of human DNP, but not diabetic mice with albuminuria." (PMID 15737001, 2005). "However, the effects of hyperglycemia on the expression of mediators of inflammation and angiogenesis (CD36), immune regulation (TLR-7 and CD69), and inflammation/tissue repair (CD274) regarding wound healing are unknown." (PMID 41465460, 2025). "However, the role of CD36 in cutaneous wound healing and the effect of hyperglycemia on its expression are yet unknown." (PMID 41465460, 2025). "Therefore, one might speculate that our unexpected observation of a 50% reduction in the fatty acid translocase CD36 alongside lipid accumulation in HepG2 cells under hyperglycemia/hyperinsulinemia might be a compensatory mechanism." (PMID 36835287, 2023). "The protein expression of CD36, CD69, and CD274 was increased with hyperglycemia compared to control cells as evidenced by increased fluorescence." (PMID 41465460, 2025). "The expression of CD36 and LOX-1 are dependent on oxidative stress induced by vascular injury and hyperglycaemia." (PMID 27809851, 2016). "We obtained similar results, in that hyperglycemia enhanced RAGE and CD36 expression and decreased ABCA1 and ABCG1 expression." (PMID 26807573, 2016). "Hyperglycemia significantly increases the expression of CD36, CD69, and CD274 and increases TLR-7 expression but not significantly in diabetic tissues compared to control tissues." (PMID 41465460, 2025). "Additionally, it inhibits the expression of Cluster determinant 36 (CD36), a hyperglycemia-induced fatty acid transporter, that increases free fatty acid uptake and reduces insulin secretion." (PMID 41234236, 2025). "Unlike the normoglycemic conditions, CD36 expression does not increase in hyperglycemia one hour after LPS activation." (PMID 31415598, 2019). "In order to evaluate the possible effects of hyperglycemia on CD36 expression in healthy subjects, an in vitro experiment was carried out using monocyte in three different conditions: extreme hyperglycemia (HG), euglycemia (EG) and in the absence of glucose." (PMID 28729885, 2017). "Hyperglycemia is an important modulator of CD36 mRNA and non-glycated protein expression in vitro, increasing de novo synthesis in healthy subjects." (PMID 28729885, 2017). "The aim of this study was to analyze CD36 expression in peripheral blood monocytes in healthy subjects in different cell culture conditions: extreme hyperglycemia (HG), euglycemia (EG) or without glucose (saline solution) (control group)." (PMID 28729885, 2017).
Hyperglycemia (continued). "Additionally, hyperglycemia, regardless of plasma FFA levels, increases the influx of FAs into cardiomyocytes by the upregulation of miR-320 and the associated increase in CD36 expression." (PMID 32796572, 2020). "Additionally, CD36 levels decrease initially at 3 h post-glucose in OLETF, ARB and MINUS, increasing further only in ARB at 6 h post-glucose, when elevated glucose levels have cleared circulation, suggesting that hepatic CD36 may not be stimulated by hyperglycemia during MetS." (PMID 34327606, 2022).
prostate carcinoma (36 papers, 2014 to 2025). A carcinoma that arises from epithelial cells of the prostate gland. "In prostate cancer, CD36‐mediated fatty acid uptake has been implicated in cancer progression and is associated with more aggressive disease, with CD36 inhibition using antibodies effectively suppressing tumor growth." (PMID 40552664, 2025). "In PTEN-deficient prostate cancer, CD36 promotes an increased FA uptake and accelerated cancer progression, which suggests that it renders cancer cells dependent on the exogenous lipid uptake." (PMID 36613455, 2022). "In particular, a high CD36 expression is associated with poor prognosis in cancers, such as breast, ovarian, gastric, and prostate cancers." (PMID 36613455, 2022). "In vivo, ablation of SR-B2/CD36 in the prostate tissue of Pten-deficient mice reduced fatty acid uptake by ~ 55%, while treating mice harboring PDXs of localized high-risk prostate cancer with a SR-B2/CD36 mAb reduced fatty acid uptake by 22%." (PMID 33413672, 2021). "The modulation of fatty acid transporter CD36 activity ameliorates free FA uptake and consequently diminishes the prostate cancer progression." (PMID 39941741, 2025). "Mechanistically, we observed that IL-8/CXCR2 signalling promotes prostate cancer cells to secrete ω−3/6 PUFAs, which are taken up by macrophages via CD36 and contribute to M2 polarization, thus fostering an immunosuppressive TME." (PMID 41163221, 2025). "In prostate cancer, the uptake of fatty acid is increased through a high CD36 expression, and treatment with the CD36 mAB antibody significantly reduces tumour volume." (PMID 38610991, 2024). "CD36, a protein that realizes the uptake of FAs into the cells, has been shown to be elevated in gastric, pancreatic, and prostate cancer at the protein level 1,7–10." (PMID 39085485, 2024). "CD36 was highly and significantly (p-value < 0.05) upregulated in prostate cancer lung metastases in comparison to prostate cancer bone metastases." (PMID 39146303, 2024). "Studies on PDXs and tumor organoids showed that fatty acid uptake is increased in prostate cancer in part mediated through overexpression of the fatty acid transporter CD36." (PMID 31366128, 2019). "Remarkably, however, both the blood vessels and the tumor cells in metastatic human prostatic carcinomas express CD36, as detected by immunohistochemistry." (PMID 29921791, 2018). "Consistent with this was the observation that Wnt1 plays a role in the regulation of CD36 via activation of the canonical Wnt pathway, and that CAV expression is closely associated with Myc in prostate cancer." (PMID 28798698, 2017). "Blocking lipid uptake by CD36 inhibition is a potential therapy for prostate cancer." (PMID 39920872, 2025). "In accordance with Yue at al.’s observations, the expression of several genes related to lipid metabolism (e.g., CD36) was decreased when PPAT explants from patients with prostate cancer who underwent radical prostatectomy were co-cultured with prostate cancer cell lines." (PMID 39941741, 2025). "FA uptake was increased in human prostate cancer via the CD36 fatty acid transporter." (PMID 39941741, 2025). "Given the more than 2fold increase of CD36 expression in prostate cancer lung metastases it can be hypothesized that CD36-expressing macrophages play a genuine role in the metastatic niche of the lung." (PMID 39146303, 2024). "Notably, C75 uniquely sensitised prostate cancer cell lines to ionizing radiation, and its effects were synergistically increased when combined with an anti-CD36 antibody." (PMID 38610991, 2024). "Interestingly, the same authors reported that near-complete ablation of SR-B2/CD36 mRNA reduced free fatty acid uptake by only 35% in PC-3 prostate cancer cells." (PMID 33413672, 2021). "Moreover, blocking CD36 in patient-derived prostate cancer xenograft (PDX) models reduces tumor growth in CD36high PDX models, suggesting a potential therapeutic benefit of blocking fatty acid uptake in CD36high prostate cancer." (PMID 33499022, 2021).
prostate carcinoma (continued). "Interestingly, CD36 also promotes fatty acid uptake, storage and modulates lipid composition in aggressive Pten mutant mouse models of prostate cancer." (PMID 33499022, 2021). "Further studies identified fatty acid translocase (FAT/CD36) as a key fatty acid transport protein in prostate cancer while inhibition of FAT/CD36 with a monoclonal antibody attenuated tumor growth in a prostate patient-derived xenograft (PDX) and PDX-derived organoids." (PMID 35127483, 2021). "Suppressing fatty acid uptake via CD36 has also been shown to inhibit prostate cancer growth." (PMID 32103057, 2020). "Therefore, we assessed the ability of a CD36 neutralizing antibody to affect viability and clonogenic survival of prostate cancer cells, either as a single agent or in combination with C75 or radiation." (PMID 33083663, 2020). "In addition to the uptake of extracellular free fatty acid through LIPF and CD36, our model also suggested that prostate cancer cells also exhibit elevated de novo fatty acid synthesis." (PMID 32103057, 2020). "In addition, CD36 expression was increased in breast cancer and prostate cancer cells co-cultured with BMA." (PMID 31334678, 2019). "In this study, the authors used patients' samples and xenograft models to demonstrate that increase in uptake and utilization of fatty acids in prostate cancer is due, at least in part, to expression of CD36, and that the presence of this transporter correlates with aggressive disease." (PMID 31922096, 2019). "CD36 represents another promising pharmacological target for interfering with the fatty acid uptake by cancer cells, and very recently, Watt and co-workers showed how targeting CD36 could be an effective strategy against prostate cancer." (PMID 31922096, 2019). "In the light of recent work in prostate cancer and other fields, it also appears likely that free fatty acids may induce or modulate the calcium signaling in epithelial prostate cancer cells via the scavenger receptor CD36." (PMID 29921791, 2018). "Understanding the mechanisms that regulate CD36 + M2 TAM infiltration and high CD47 expression in tumour cells within the prostate cancer tumour microenvironment (TME) is essential." (PMID 41163221, 2025). "In many types of cancer, including breast, ovarian, gastric and prostate cancers, a high expression of CD36 (fatty acid translocase) was found." (PMID 37298551, 2023). "For instance, the fatty acid translocase CD36 is upregulated in oral and prostate cancer cells, thus increasing the synthesis and uptake of β-oxidized lipid and driving metastatic outgrowth." (PMID 34685686, 2021). "Top enriched genes in cSCs included stem-cell-related genes PSCA, CD36, and SPINK1, among others not previously associated with prostate cancer stem-like cells." (PMID 34360875, 2021).
Stroke (36 papers, 2009 to 2026). Sudden impairment of blood flow to a part of the brain due to occlusion or rupture of an artery to the brain. "Still, the GWAS of the four large cohorts (19,602 white people, including 1544 stroke cases) showed instead that CD36 rs3211928 was significantly associated with stroke." (PMID 37239003, 2023). "In the present study, we aimed to evaluate the effect of platelet CD36 on overweight-associated stroke risk or prothrombotic phenotype in NVAF patients." (PMID 36465448, 2022). "Our objective was to evaluate the effect of platelet CD36 on the risk of stroke associated with overweight in NVAF patients." (PMID 36465448, 2022). "A genome-wide association study (GWAS) of the four large cohorts (19,602 white people in whom 1544 cases of stroke) showed that CD36 rs3211928 was significantly associated with stroke." (PMID 35396566, 2022). "On the other hand, CD36 exhibits associations with known predisposing factors to stroke, emphasizing its complex and dynamic function." (PMID 33498620, 2021). "Because increases in LDL and AGE are associated with acute ischemic stroke incidence, CD36 is considered a particularly important tool when evaluating effective targets for the regulation of stroke outcomes." (PMID 33498620, 2021). "Thus, Nrf2 activation is an important regulatory mechanism underlying CD36-mediated phagocytosis following stroke." (PMID 37601043, 2023). "The CD36 antagonist SSO has been shown to mitigate stroke-induced neuroinflammation and confer neuroprotection in murine models of ischemic stroke." (PMID 38840180, 2024). "Because CD36+ MGs/MΦs specifically appeared within ischemic areas after stroke, our findings suggest that the L-PGDS–PGD2–DP1 axis plays an important role in brain tissue repair by regulating phagocytic activities of CD36+ MGs/MΦs." (PMID 39451255, 2024). "In conclusion, the scavenger receptor CD36, as an essential phagocytic receptor, exerts complex effects following stroke." (PMID 37601043, 2023). "CD36 has a restorative function during the resolution phase, suggesting that the mechanism of CD36 depends on the environment and timing of the stroke." (PMID 37452512, 2023). "Evidence suggests that the effects of genetic deletion of CD36 in acute neonatal stroke are, in part, due to the diminished phagocytosis of apoptotic neurons in injured neonatal brain and the consequent accumulation of the caspase-3 positive cells." (PMID 36759676, 2023). "SSO, an inhibitor of CD36, inhibits cellular uptake of long-chain fatty acids and reduces neuroinflammation after stroke." (PMID 37305546, 2023). "CD36 expression is low in the normal brain and significantly enhanced following stroke, mainly in macrophages in the brain." (PMID 37601043, 2023). "In the adult, synergy of CD36 signalling between the periphery and the injured brain after stroke, along with induced BBB leakage, has been demonstrated." (PMID 35148760, 2022). "In stroke and under neurodegenerative conditions in the adult and ageing brain, CD36 has been found harmful." (PMID 35148760, 2022). "Altogether, our data suggest cooperation between blood–CSF–brain interface via the CP through CD36-mediated signalling following neonatal stroke with a key role for inflammatory monocytes and neutrophils." (PMID 35148760, 2022). "It is possible that oxLDL and other endogenous ligands are released after stroke, activating CD36-inflammasome signalling in the CP and contributing to inflammatory response." (PMID 35148760, 2022). "CD36 was shown to contribute to stroke, neurodegenerative diseases and dementia and is being considered as a therapeutic target during adulthood and aging." (PMID 35148760, 2022). "In stroke, CD36 was found to provide a context-dependent function involving inflammation and resolution with either beneficial and detrimental outcome effects." (PMID 35177618, 2022).
Stroke (continued). "Further implications of CD36 in neonatal stroke as compared to adult stroke are to be revealed by the use of pharmacological inhibitors/activators of CD36 in the neonatal stroke model." (PMID 35148760, 2022). "While these findings attest to an injurious role of CD36, its role in monocytes and macrophages in mediating phagocytosis during the resolution phase of stroke has also been demonstrated, suggesting potentially beneficial aspects of CD36 signalling." (PMID 35148760, 2022). "We observed marked differences between WT and CD36 KO of multiple well-described inflammatory players in neonatal stroke and hypoxia–ischemia, including down-regulation of Tlr4, Timp1, Csf-1 and CD68." (PMID 35148760, 2022). "In stroke and ischemia models, increased expressions of CD36 were demonstrated mainly by microglial cells in a PPARγ-dependent manner, which was associated with the resolution of neuroinflammation through phagocytosis." (PMID 36310859, 2022). "Translational impact of our study is demonstration of brain maturation-dependent effects of CD36 after stroke." (PMID 35148760, 2022). "Together, these data suggest cooperation between peripheral and brain CD36—mediated signalling following neonatal stroke via the CP." (PMID 35148760, 2022). "In stroke-prone SHRs, increased expression of CD36 in microglia and associated BBB lesions were demonstrated, indicating a pro-inflammatory role of CD36 in the brain under hypertensive conditions." (PMID 34868060, 2021). "Considering the soluble form of CD36, an increase in circulating pro-inflammatory protein levels can increase stroke incidence and substantially exacerbate outcomes." (PMID 33498620, 2021). "Our results showed there were significant reductions of both PPARγ downstream genes after stroke (there was 96.8% reduction in CD36 mRNA level and 73% reduction in FABP4 mRNA level) in db/db mice compared to those in db/+ mice." (PMID 32012810, 2020). "An unexpected finding is that preconditioning with a CD36 inhibitor can reduce the effects of stroke." (PMID 32174916, 2020). "The rFGF21 administration given 6 h after stroke eliminated this reduction (263.8% increase in CD36 and 199.6% increase in FABP4), which reflected the change of cerebrovascular PPARγ activity." (PMID 32012810, 2020). "With high affinity toward apoptotic cells and many ligands such as thrombospondins (TSPs), fibrillary amyloid β and oxidized lipids, CD36 has been suggested to play a pivotal role in the clearance of cell debris during the recovery phase in post-stroke brains." (PMID 31447626, 2019). "Stroke induces increased mRNA expression of CD36 and TSP-1/2 mRNA levels in the ipsilateral hemisphere both during the acute and recovery phases." (PMID 31447626, 2019). "However, the expression of microglial scavenger receptor Cd36 (Scarb3), which was reported as related to phagocytic activities in post-stroke mouse brains, was significantly upregulated in MGs/MΦs following PGD2 treatment." (PMID 39451255, 2024). "Contrary, CD36 can promote neovascularization and scar formation worsening post-stroke recovery." (PMID 35237675, 2022). "The most significantly upregulated genes, including Lpl, Spp1, Cd36, Mmp2, and Mmp19, and the most highly enriched genes, including Cd5l, Mmp3, Mmp12, and Mmp13, indicate a pronounced disturbance in lipid homeostasis in infarcts at 7 weeks after stroke." (PMID 34819339, 2022). "Despite its apparent detrimental role in ischemic damage through activation of inflammation and ROS, CD36 may also exert a beneficial role during post-stroke and post-MI resolution phase of inflammation by mediating phagocytosis." (PMID 35237675, 2022). "Therefore, there is a foundation for continued preclinical research into the soluble form of CD36 and the dynamic functions it plays in alleviating detrimental stroke outcomes." (PMID 33498620, 2021). "Similarly, during the resolution phase of stroke, CD36 macrophages have a reparative role through phagocytosis." (PMID 34316406, 2021).